MYC (MYC proto-oncogene, bHLH transcription factor)
Diseases named in the same sentence as MYC in open-access papers (continued):
Sharing a sentence is not in itself a finding about the gene and the disease.
breast tumors (continued). "Human microRNA-1204, which is residing in 60 kb downstream of MYC and within the exon 1b of PVT1, depresses tumor suppressor genes and contributes to ovarian and breast tumor proliferations and patients’ survival." (PMID 29079774, 2017). "We measured the extent to which the transcriptomes of breast tumors with amplifications of ERBB2, MYC or CCND1 oncogenes are due to the accompanying onco-passenger CNVs." (PMID 29069713, 2017). "One of the most significant partnerships of MYC in both breast and uterus cancer cells involves ERBB2, whose effect on the over-expression of the TF in HER2+ breast tumors has been noted before." (PMID 26792175, 2016). "The circuit formed by MYC and the pair CDKN2A/CDKN2B also appears very significant in breast tumors, in coherence with the role that MYC amplification has on the enhancement of cell cycle de-regulation." (PMID 26792175, 2016). "For example, subgroup 10 gathered breast tumours in which the GSTP1 and SERPINB5/maspin as well as the MAD2L1 and MYC genes, which specify basal-type adenocarcinomas, were over-expressed." (PMID 17338809, 2007). "We conclude that transduction of normal HMECs with lentiviruses expressing ERα, BMI1, MYC and TERT confers the ability to form metastatic ERα-positive breast tumours." (PMID 17573968, 2007). "MYC, which is a gene that was down-regulated by LPP2 KO in our array, is an important proto-oncogene that promotes cell cycle progression and is highly expressed in breast tumors." (PMID 35966578, 2022). "We did not observe a significant correlation between LPP2 and MYC in human breast tumors (results not shown)." (PMID 35966578, 2022). "Moreover, c-MYC activation links to TCA cycle overactivation in HER2-positive and TN breast tumors by increasing the uptake of serine, glycine, and tryptophan and the synthesis of one-carbon units." (PMID 33489906, 2020). "Further, activated RAS/PI3K/MYC/E2F signaling is also the feature of these ER negative, basal and aggressive breast tumors." (PMID 24147022, 2013). "However, the regulation of c-MYC by miR-32-5p in breast neoplasms has not been mechanistically examined." (PMID 40711670, 2025). "In our previous work, we observed that MYC was regulated at the protein level, with high levels of pS62-MYC and low levels of pT58-MYC in breast tumor cell lines and tumor tissue relative to non-transformed mammary cell lines and adjacent normal breast tissue, respectively." (PMID 32895364, 2020). "This may be due to MYC-mediated monopolization of the protein translation machinery and regulation of the translation factors eIF4E, eIF4A, and eIF4G and could explain in part how TA suppresses breast tumor growth in animal models without evidence of toxicity." (PMID 35095503, 2021).
acute lymphoblastic leukemia (113 papers, 2008 to 2026). Leukemia with an acute onset, characterized by the presence of lymphoblasts in the bone marrow and the peripheral blood. "However, the loss of CTCF and consequently TAD fusion occurred in T-ALL (acute lymphoblastic leukemia), resulting in the establishment of spatial interactions between MYC and super-enhancer and the up-regulation of MYC." (PMID 35580989, 2022). "MYC-translocated T-lineage acute lymphoblastic leukemia (T-ALL) is a rare subgroup of T-ALL associated with CDKN2A/B deletions, PTEN inactivation, and absence of NOTCH1 or FBXW7 mutations." (PMID 30304769, 2018). "In a study with lymphoblastic leukemia, they showed that MYC overexpression enhances the UPR system and simultaneously the ERAD system through transcriptional upregulation of UFD1." (PMID 40579643, 2025). "Conversely, TIP60 promoted histone H4 acetylation and cell cycle progression via MYC in B-lineage acute lymphoblastic leukemia cells." (PMID 40612865, 2025). "A constitutive IRS1 and β-catenin protein interaction activated MYC expression in Acute Lymphoblastic Leukemia Cells." (PMID 32851100, 2020). "Of clinical relevance, MYC positivity was found to confer good response to the acute lymphoblastic leukemia (ALL)–based chemotherapy in a limited number of patients." (PMID 31035408, 2019). "Conversely, deregulation of MYC, either by MYC gene translocation or by Notch-driven MYC overexpression, impairs T cell development and induces T cell acute lymphoblastic leukemia (T-ALL)." (PMID 28245597, 2017). "Sphk2 has also been shown to have an oncogenic role in acute lymphoblastic leukemia by enhancing MYC expression." (PMID 26956050, 2016). "Comprehensively, MYC chromosomal translocations and MYC amplifications are also found in other aggressive hematological neoplasms such as plasmablastic lymphoma, transformed follicular lymphoma, and lymphoblastic leukemia." (PMID 41008653, 2025). "In addition, the proto–oncogene MYC and interleukin 2 receptor subunit Alpha (IL2RA) are implicated in the prognosis of acute lymphoblastic leukaemia." (PMID 32887470, 2020). "SHQ1 facilitates MYC RNA splicing to promote T-acute lymphoblastic leukemia (T-ALL) development." (PMID 32522979, 2020). "SphK2 is important for MYC expression to promote acute lymphoblastic leukemia progression." (PMID 29285269, 2017). "The expression of DLST was significantly upregulated in MYC-over-driven T-cell acute lymphoblastic leukemia (T-ALL) and primary T-ALL patient samples." (PMID 40897695, 2025). "In both B-cell and T-cell acute lymphoblastic leukemia (ALL), SEs dysregulation drives transformation by overexpressing oncogenes like MYC and TAL1, often through alterations in lineage-specific transcription factors." (PMID 41268574, 2025). "In MYC-rearranged B-cell precursor acute lymphoblastic leukemia (BCP-ALL), which is common in pediatric cases and typically characterized by the absence of smIg and light chains, some instances have also shown characteristics of mature B cells." (PMID 41142614, 2025). "Another study proposed that c-MYC inhibition sensitizes acute lymphoblastic leukemia (ALL) to chemotherapy by altering caspase-3-dependent apoptosis and autophagy by targeting the PI3K pathway." (PMID 36691066, 2023). "In human primary T cell acute lymphoblastic leukemia samples, a topologically associating domain ‘fusion’ event due to CTCF-mediated insulation absence results in the interaction between distal super-enhancers and the MYC gene promoter, leading to MYC over-expression and leukemogenesis." (PMID 38135679, 2023).
acute lymphoblastic leukemia (continued). "Notably, it has been shown that GATA3 could promote leukemic transformation by driving MYC enhancer activity, and inherited GATA3 variants are associated with Ph-like childhood acute lymphoblastic leukemia and risk of relapse." (PMID 34980123, 2022). "In a Tet-off transgenic mouse model of MYC-induced T cell acute lymphoblastic leukemia (T-ALL), PD-L1 and MYC expression were significantly correlated." (PMID 35907881, 2022). "MYC upregulates PD-L1 expression in T cell acute lymphoblastic leukemia (T-ALL) cells by directly binding to the promoter region of PD-L1, suggesting that the EGFR pathway is able to upregulate PD-L1 by upregulating MYC and promoting nuclear translocation." (PMID 35279217, 2022). "A recent study have indicated that SHQ1 is highly expressed in T-acute lymphoblastic leukemia (T-ALL) and promotes the development of T-ALL through promoting MYC RNA splicing." (PMID 32522979, 2020). "PVT1 also regulates MYC in acute lymphoblastic leukemia (ALL) where PVT1 can act as an oncogene and drives both the development and progression of this type of blood cancer." (PMID 33134177, 2020). "The MYC oncogene is involved in the pathogenesis of 60–70% of all human cancers, including T cell acute lymphoblastic leukemia (T-ALL)." (PMID 31266538, 2019). "The typical phenotype of BL (CD19 + /CD10 + /BCL2-/Ki67 > 95%/TdT-/CD34-/sIg +) with appropriate cytomorphology, demonstration of MYC-R alone, and simple karyotype differentiates MYC/BCL2 “double hit” lymphomas and lymphoblastic leukemia/lymphoma." (PMID 37530792, 2024). "In acute lymphoblastic leukaemia (ALL), lncPVT1 increases MYC protein levels with the resulting driver effects on primary tumours." (PMID 34754096, 2022). "T-cell acute lymphoblastic leukemia (T-ALL) is an aggressive hematologic malignancy of developing thymocytes that often harbors gain-of-function mutations of NOTCH1, leading to aberrant activation of its downstream gene MYC." (PMID 35740646, 2022). "Perphenazine (PPZ), a drug approved for psychosis therapy, was found to be effective against T-cell acute lymphoblastic leukemia (T-ALL) in a combined screening for small molecules with toxic effect in MYC-overexpressing thymocytes in zebrafish and T-ALL cells." (PMID 35565373, 2022). "For example, in a lymphoblastic leukemia cell model, ABC294640 inhibited expression of both MYC and c-Myc–regulated genes; it also reduced cell proliferation and survival." (PMID 32615066, 2020). "Here, we report that in T cell acute lymphoblastic leukemia (T-ALL) the MYC oncogene controls the expression of TET1 and TET2 to maintain 5-methylcytosine (5mC) and 5-hydroxymethylcytosine (5hmC) patterns, which is associated with tumor cell-specific gene expression." (PMID 31266538, 2019). "Oncogenes, such as MYC, RAS, and BCR-ABL, are frequently involved in the pathogenesis of human acute lymphoblastic leukemia (ALL)." (PMID 27095570, 2016). "In a tetracycline-regulated conditional mouse model of MYC-induced T cell Acute Lymphoblastic Leukemia (T-ALL), the tumor cells undergo proliferative arrest and death within 2 days of turning off the MYC oncogene via tumor intrinsic, host independent, immune independent mechanisms." (PMID 25089198, 2014). "Consequently, disrupting the interaction between ZBTB17 and MYC may render current acute lymphoblastic leukemia (ALL) chemotherapies more effective." (PMID 34349770, 2021). "MYC, CXCL8, and ATF3 were considered the hub genes and queried on Oncomine database and cBio portal platform to investigate their gene expression and genetic alterations in lymphoblastic leukemia." (PMID 32096603, 2020). "In T cell acute lymphoblastic leukemia (T-ALL), recurrent TAD fusion events at the MYC locus, a key oncogene downstream of NOTCH1 signaling, are consistently observed." (PMID 40901634, 2025).
acute lymphoblastic leukemia (continued). "For example, the epistatic activation of MYC, for instance, via NOTCH1 signaling in T-cell acute lymphoblastic leukemia (T-ALL) is essential to tumorigenesis (22, –24)." (PMID 36897988, 2023). "Here we report that in MYC-, RAS-, and BCR-ABL-induced acute lymphoblastic leukemia (ALL), apoptosis upon oncogene inactivation is mediated by the same pro-apoptotic protein, BIM." (PMID 27095570, 2016). "For example, in T-cell acute lymphoblastic leukemia (T-ALL) deletion of a TAD boundary fuses the neighboring TADs resulting in the abnormal interaction of the MYC gene promoter with the BDME gene enhancer, inducing MYC transcription upregulation." (PMID 38020908, 2023). "Growth arrest‐specific (GAS2) interacts with C‐X‐C motif chemokine receptor 4 (CXCR4) and enhances the stability of CXCR4 in T‐cell acute lymphoblastic leukemia (T‐ALL) cells, and the GAS2/CXCR4 axis activates the expression of NOTCH/c‐MYC and promotes T‐cell leukemogenesis." (PMID 36054080, 2022). "Similarly, in human T cell acute lymphoblastic leukemia (T-ALL), NOTCH MYC enhancer (N-Me) acts as a critical mediator of NOTCH1 induced MYC expression required for T cell development and T cell transformation." (PMID 31311566, 2019). "c-MYC is also frequently reported to be upregulated in acute lymphoblastic leukemia (ALL), however, the correlation of c-MYC expression with clinical features of ALL has not been fully described." (PMID 26517351, 2015). "Interestingly, aberrant NOTCH signaling is observed in both human and murine T cell acute lymphoblastic leukemia (T-ALL), and NOTCH inhibition in T-ALL lines suppresses mTOR activation by inhibiting c-MYC expression." (PMID 25653651, 2014). "Indeed, we and others have previously suggested that induction and maintenance of T-cell acute lymphoblastic leukemia (T-ALL), a devastating pediatric blood cancer, depends on the cross talk of three transcription factors, NOTCH1, MYC, and RELA (NF-κB)." (PMID 21356087, 2011). "The NUP214-ABL1 fusion kinase, which is frequently observed in acute lymphoblastic leukemia (ALL), has a vital function in facilitating the cooperative attachment of TLX1 and STAT5 to enhancers, thus triggering the activation of significant oncogenes such as MYC and BCL2." (PMID 39838405, 2025).
small cell lung carcinoma (99 papers, 2010 to 2026). Small cell lung cancer (SCLC) is a highly aggressive malignant neoplasm, accounting for 10-15% of lung cancer cases, characterized byrapid growth, and early metastasis. "The MYC amplifications is noted in 15-20% of individuals diagnosed with small-cell lung cancer, and implicated in chemoresistance, tumor progression, or poor survival." (PMID 41510169, 2026). "Resistance mechanisms, such as the bypass signaling pathway, PTEN loss, MET amplification, MYC amplification, and small cell lung carcinoma transformation, have been described in previous reports." (PMID 38012343, 2023). "Furthermore, MYC, as a driver of susceptibility to Aurora kinase inhibition in small cell lung cancer cells and tumors 45, was enriched in KLB down genes." (PMID 31695781, 2019). "Further confirming the role of MYC in glycolysis were the results from a small-cell lung carcinoma (SCLC) xenograft model, where it has been shown that MYChigh tumors are more sensitive to glycolysis inhibition." (PMID 40126351, 2025). "Although MYC levels were higher in small cell lung cancer, 31%, and high‐grade neuroendocrine tumors, 17%, the expression level of MYC still fell short of expectations." (PMID 41194439, 2025). "Our findings indicate that the BRCA1 and MYC/MYCN-RAD51 axes govern the response of small cell lung cancer to BI-2536 and its combination with alisertib." (PMID 39085197, 2024). "Chalishazar and colleagues have shown that MYC-driven small-cell lung cancer depends on arginine and polyamine levels for growth, and that depletion of arginine suppresses tumor growth and promotes the survival of mice with MYC-driven tumors." (PMID 38761252, 2024). "Previous studies have demonstrated that the phosphorylation of STAT3/MYC by CSF2 regulates the phenotypic plasticity of small cell lung cancer." (PMID 38817867, 2024). "For the first time, our study demonstrates that in small cell lung cancer cells, the sensitivity to BI-2536 and the synergistic effect of its combination with alisertib are modulated by the MYC/MYCN-RAD51 axis." (PMID 39085197, 2024). "The L-MYC gene was initially discovered in small-cell lung cancer based on homology to both c-MYC and MYCN." (PMID 37046804, 2023). "For example, a double-minute (DM) chromosome containing the MYC proto-oncogene (MYC) is generated in the small-cell lung cancer cell line SCLC-21H through chromothripsis." (PMID 35494014, 2022). "A similar finding was made for MYC in response to THZ1 in MYC-amplified SCLC (small cell lung cancer) cells." (PMID 35053227, 2022). "The transfection of MYC enhanced the in vitro proliferation rate of human small-cell lung cancer cells." (PMID 35437508, 2022). "Several recurring genetic aberrations including MYC have been found in small cell lung cancer (SCLC)." (PMID 35033084, 2022). "These were designed to inhibit the proliferation of high-MYC expressing (MYC family oncogenes) expressing small-cell lung cancer cell line." (PMID 34500603, 2021). "For example, amplification of MYCL or the presence of the RLF-MYCL1 fusion gene are mutually exclusive of amplifications of MYC or MYCN in small cell lung cancer." (PMID 29028833, 2017). "Intriguingly, one study found that a significant number of MCC tumors contained genomic amplification of MYCL, a close relative of MYC that is also amplified in small cell lung cancer." (PMID 27880818, 2016).